GLO1 (glyoxalase I)
Diseases named in the same sentence as GLO1 in open-access papers (continued):
Sharing a sentence is not in itself a finding about the gene and the disease.
prostatic intraepithelial neoplasia (2 papers, 2021 to 2023). "However, GLO1 expression has not been explored in the context of PCa progression with a focus on high-grade prostatic intraepithelial neoplasia (HGPIN), a frequent precursor to invasive cancer." (PMID 34298821, 2021).
psoriasis (2 papers, 2020 to 2025). An autoimmune condition characterized by red, well-delineated plaques with silvery scales that are usually on the extensor surfaces and scalp. "Methotrexate, a drug used in psoriasis therapy, inhibits Glo1 activity, promoting MG accumulation." (PMID 39982364, 2025). "However, RNA expression profiling of uninvolved and lesion skin from psoriasis patients showed decreased expression of Glo1." (PMID 33396745, 2020).
Sepsis (2 papers, 2014 to 2021). Sepsis is defined as life-threatening organ dysfunction caused by a dysregulated host response to infection. "However, it was also found that patients with sepsis syndrome had a significant reduction in the expression of mononuclear GLO-1, suggesting that patients with sepsis are more susceptible to the accumulation of MG through the loss of the GLO-1 rather than the loss of an essential cofactor." (PMID 25498125, 2014). "Down-regulation of GLO-1 is a possible mechanism leading to cell damage andmulti-organ failure in sepsis with intervention potential." (PMID 34156474, 2021). "Down-regulation of GLO-1 is a possible mechanism leading to cell damage andmulti-organ failure in sepsis with intervention potential, urging furtherinvestigation of the glyoxalase pathway in sepsis." (PMID 34156474, 2021). "In comparison with healthy volunteers, expression of GLO-1, the key enzyme of the MG detoxification pathway, was shown to be significantly reduced in patients with septic shock within the first 24 hours after sepsis onset (S/T0, S/T1)." (PMID 25498125, 2014).
steatosis (2 papers, 2019 to 2025). Increased lipid within the cytoplasm of cells. "Several studies have shown that Glo-1 expression in the liver is decreased in response to both high-fructose and high-fat diets, and increased levels of AGEs in the liver have been associated with steatosis severity in patients with NAFLD." (PMID 31438528, 2019). "After 12 and 16 weeks of HFD feeding ApoE−/− mice developed minimal to mild steatosis and showed significantly decreased expression of Glo1 in comparison with upregulated Glo1 in ApoE−/− mice on a normal diet." (PMID 40141037, 2025).
acute myeloid leukemia (1 paper, 2021). Acute myeloid leukemia (AML) is a group of neoplasms arising from precursor cells committed to the myeloid cell-line differentiation. "The impaired GLO1 activity is associated with the decreased GSH concentration and with the induced apoptosis of acute myeloid leukemia cells." (PMID 34671271, 2021).
aging (1 paper, 2019). A developmental process that is a deterioration and loss of function over time. "To date, involvement of Glo-1 in OA has only been speculated since OA is an AGE-related disease model and because Glo-1 is involved in aging diseases." (PMID 30635030, 2019).
anaplastic thyroid cancer (1 paper, 2021). "Of interest, it has also recently been shown that blocking the IL-1 receptor activity partially up-regulates GLO1 in anaplastic thyroid cancer cells." (PMID 34835243, 2021).
aortic atherosclerosis (1 paper, 2014). A atherosclerosis that involves the aorta. "Aortic atherosclerosis was also quantified in 22‐week‐old, male normoglycemic Glo1 knockdown mice on an Apoe−/− background (Glo1KDApoe−/− mice), an age at which Glo1KD mice exhibit albuminuria and renal pathology similar to that of diabetic mice." (PMID 24920125, 2014). "Male Apoe−/− mice, hemizygous for a human GLO1 transgene (GLO1TGApoe−/− mice) or male nontransgenic Apoe−/− litter mates were injected with streptozotocin or vehicle and 6 or 20 weeks later, aortic atherosclerosis was quantified." (PMID 24920125, 2014).
astrocytoma (1 paper, 2010). "Treatment of U-373 astrocytoma cells with 25, 50, and 100 μM TRG evoked a substantial decrease in the GLO-1 enzyme at the last 24-hour time point before cells were no longer viable for harvesting." (PMID 20454582, 2010).
Azoospermia (1 paper, 2023). Absence of any measurable level of sperm,whereby spermatozoa cannot be observed even after centrifugation of the semen pellet. "The expression levels of GPR135 in azoospermia tissues positively correlated with the levels of “DYNLL2” and “EPB41L3” and negatively correlated with GLO1 expression." (PMID 37283758, 2023). "The results indicated that the score of “GLO1” was significantly negative correlated with the CIBERSORT scores of “Th1 cells” (R > 0, P < 0.01), and the immune expression pattern of GLO1 in azoospermia patients was opposite to that of the other three genes." (PMID 37283758, 2023).
brain tumors (1 paper, 2018). "The implication of GLO1 overexpression in brain tumors to patients’ outcomes was examined using PROGgeneV2, a web tool for querying prognostic implications of genes in various cancers." (PMID 29385725, 2018). "BLI data acquired at days 14 and 17 revealed significant diminution of brain tumors in GLO1 inhibitor-treated mice but not in vehicle-treated mice." (PMID 29385725, 2018).
cerebral cavernous malformation (1 paper, 2020). A disorder characterized by malformations in the structure of the capillaries in the brain. "GLO1 overexpression was already associated with protective effects against neuroglial and vascular lesions, and its mutations could be involved in cancer onset, as well as in several genetic pathologies like cerebral cavernous malformations (CCMs) and retinitis pigmentosa." (PMID 32413970, 2020).
cervical cancer (1 paper, 2024). A primary or metastatic malignant neoplasm involving the cervix. "In vitro experiments indicated that GLO1 inhibition by S-p-bromobenzylglutathione cyclopentyl diester decreased cell viability and migration in cervical cancer cell lines." (PMID 38870176, 2024). "Single-cell RNA sequencing (scRNA-seq) and gene set variation analysis were utilized to investigate the role of GLO1 in the metabolism of cervical cancer." (PMID 38870176, 2024).
chronic pancreatitis (1 paper, 2019). A chronic inflammatory process causing damage and fibrosis of the pancreatic parenchyma. "Binary logistic regression results of the GLO1 single nucleotide polymorphisms in patients with alcoholic and non-alcoholic chronic pancreatitis with covariate sex." (PMID 31661534, 2019). "Common GLO1 variants do not increase chronic pancreatitis risk." (PMID 31661534, 2019).
cocaine addiction (1 paper, 2023). "Future experiments targeting specific subregions or cell types of the amygdala will be necessary to further characterize the effects of GLO1 inhibition on cocaine addiction-related phenotypes." (PMID 37798411, 2023). "Our results emphasize the importance of cellular energetics and GABAA-mediated signaling in the enduring effects of cocaine use, and identify GLO1 as a potential new target for the treatment of cocaine addiction." (PMID 37798411, 2023).
cystic fibrosis (1 paper, 2024). Autosomal recessive disorder caused by pathogenic variants in the CFTR gene (cystic fibrosis transmembrane conductance regulator), which encodes a chloride and bicarbonate channel expressed in epithelial cells, and follow the diagnosis criteria. "For example, cystic fibrosis, a genetic disease caused by mutations in the CF transmembrane conductance regulator (CFTR) gene, is associated with low Glo1 and a GSH deficiency." (PMID 39386711, 2024).
Dyskinesia (1 paper, 2021). A movement disorder which consists of effects including diminished voluntary movements and the presence of involuntary movements. "Administration of AAV2/9-Endo-Glo1 also attenuated the dyskinesia and the dyssynchrony." (PMID 34970611, 2021).
endotoxemia (1 paper, 2021). "This could lead to an accumulation of dicarbonyls.However, in these healthy men, the GLO-1 expression normalized during the 8-hourexperiment, reflecting a transient effect of endotoxemia." (PMID 34156474, 2021).
epileptic seizures (1 paper, 2018). "Moreover, recombinant inbred strains of C57BL/6J and DBA/2J mice (BXD) that inherited a genomic duplication of GLO1 showed an approximately twofold increase in GLO1 expression and an association with increased susceptibility to epileptic seizures at high atmospheric pressure." (PMID 29556176, 2018).
gastric tumor (1 paper, 2012). "Strong staining for GLO1 was frequently observed in advanced gastric tumor cells, in contrast to weak or no staining in normal gastric epithelial cells." (PMID 22479608, 2012).
HIV-1 infection (1 paper, 2021). The type species of lentivirus and the etiologic agent of acquired immunodeficiency syndrome (AIDS). "Administration of AAV2/-Endo-Glo1 five weeks post-HIV-1 infection blunted the upregulation of MG-H1, VAP-1 and the loss of Glo1 seen in hearts of Hu-mice, seventeen weeks post-HIV-1 infection." (PMID 34970611, 2021). "Administration of AAV2/-Endo-Glo1 blunted the upregulation of the loss of CD31 seen in the myocardium of Hu-mice 16 weeks post-HIV-1 infection." (PMID 34970611, 2021). "In this study we found that after seventeen weeks of HIV-1 infection, cardiac Glo1 level was 40.2 ± 3.5% lower than that in control animals." (PMID 34970611, 2021). "A single intravenous injection of AAV2/9-Endo-Glo1 to hu-mice five weeks after HIV-1 infection, increased myocardial Glo1 protein and attenuated the increase in VAP-1 as observed at seventeen weeks following viral infection." (PMID 34970611, 2021). "A single intravenous injection of AAV2/9-Endo-Glo1 five weeks after HIV-1 infection, attenuated the increases in plasma MG and SSAO as observed at 16 weeks of infection with minimal change in HIV-1 viremia." (PMID 34970611, 2021). "Administration of AAV2/9-Endo-Glo1 five weeks after HIV-1 infection blunted the increase in interstitial and perivascular fibrosis seen after 17 weeks post-infection." (PMID 34970611, 2021). "Intravenous administration of AAV2/9-Endo-Glo1 to Hu-mice five weeks after HIV-1 infection blunted the impairment in microvascular permeability and microvascular leakage seen in heart at seventeen weeks post-infection." (PMID 34970611, 2021). "However, under inflammatory as is the case in HIV-1 infection, activated NF-κB would compete with Nrf2 to suppress Glo1 expression." (PMID 34970611, 2021).
Hypoglycemia (1 paper, 2025). A decreased concentration of glucose in the blood. "Metabolic dysregulation was also observed in a sex-dependent manner, including increased muscle mass, hypoglycemia as well as decreased TC, TG and HDL in male Glo1+/− mice, whereas increased circulating TG and VLDL and impaired glucose tolerance was observed in female Glo1+/− mice." (PMID 39896461, 2025).
injury (1 paper, 2016). Damage inflicted on the body as the direct or indirect result of an external force, with or without disruption of structural continuity. "Furthermore, it was found that overexpression of GLO1 in rats prevented histological and functional damage after renal ischemia-reperfusion injury." (PMID 27999356, 2016).
ischemic disease (1 paper, 2017). Lack of blood supply to an area of the body, resulting in impairment of tissue oxygenation. "Notwithstanding its limitations, the present results suggest that modifying diabetic ADSCs with GLO1 can effectively elevate the therapeutic efficiency and promote stem cell therapy for the treatment of diabetic patients with ischemic diseases." (PMID 28170200, 2017).
larynx cancer (1 paper, 2021). A primary or metastatic malignant neoplasm involving the larynx. "Glo1 was found to be increased in erythrocytes of the patients following radiotherapy for larynx cancers." (PMID 34208417, 2021).
mental disorder (1 paper, 2025). A disease that has its basis in the disruption of mental process. "Several studies have suggested that GLO1 inhibitors may serve as promising therapeutic agents for mental disorders." (PMID 40826483, 2025).
mesangial sclerosis (1 paper, 2014). "The STZ‐induced increase in MG, CEL, and immunoreactive MG‐H1 in the kidney of Apoe−/− mice was largely prevented by the human GLO1 transgene and this was associated with reduced mesangial sclerosis and albuminuria." (PMID 24920125, 2014).
morbid obesity (1 paper, 2021). An excess of body weight, normally defined as an individual with a body mass index greater than 35 or a body weight greater than one hundred percent of ideal body weight. "Our first hypothesis was that compared to obese subjects, AGER/DIAPH1 expression in adipose tissue would be significantly higher in subjects with morbid obesity whereas lower expression of mRNA transcripts encoding the AGE-detoxifier enzyme GLO1 was predicted in those individuals." (PMID 34103691, 2021).
Myocardial fibrosis (1 paper, 2021). "Second, we found that increasing Glo1 in the heart of HIV-1-infected hu-mice attenuated perivascular and interstitial fibrosis indicating that the myocardial fibrosis that developed in hearts of HIV-infected Hu-mice were linked to elevated MG." (PMID 34970611, 2021).
myocardial ischemia (1 paper, 2019). A disorder of cardiac function caused by insufficient blood flow to the muscle tissue of the heart. "The effects of Glo1 overexpression was evaluated using in vitro and in vivo models of myocardial ischemia." (PMID 31534514, 2019).
opioid use disorder (1 paper, 2025). A substance-related disorder that involves the recurring use of opioids despite negative consequences. "The goal of these studies was to extend the recent work to determine whether GLO1 can modulate other behaviors related to the rewarding effects of cocaine and oxycodone, and whether GLO1 may be a target for opioid use disorder." (PMID 40412584, 2025).
oropharyngeal tumors (1 paper, 2020). "Importantly, there is recent evidence that GLO1 plays a critical role in invasion and metastasis of oropharyngeal tumors, in addition to initiation and maintenance of tumor growth." (PMID 32872541, 2020).
osteosarcoma (1 paper, 2015). A usually aggressive malignant bone-forming mesenchymal neoplasm, predominantly affecting adolescents and young adults. "Two proteins were increased (GLO1, CTSD) and the other two were decreased (RANBP1, STMN1) in osteosarcomas and metastases based on the 2-DE expression profile." (PMID 26203049, 2015).
pancreatic cancer (1 paper, 2025). "Additionally, clinical data demonstrate that elevated GLO1 expression is associated with poorer survival outcomes in pancreatic cancer patients." (PMID 40908564, 2025). "Additionally, we demonstrate a clinical‐pathological correlation between high GLO1 expression and reduced survival in pancreatic cancer patients." (PMID 40908564, 2025).
pancreatic NET (1 paper, 2017). "Metastatic tissue was available only from one patient with pancreatic NET, with a low GLO1 copy number of 0.82." (PMID 29100361, 2017). "In tissue from additional metastases resection (18 midgut NET and one pancreatic NET), GLO1 copy number was also increased, compared with healthy tissue; but was not significantly different compared with primary tumour tissue." (PMID 29100361, 2017). "For pancreatic NET, there were 4 tumours with unchanged GLO1 copy number, 4 tumours had decreased GLO1 copy number and 6 had increased GLO1 copy number (P<0.001)." (PMID 29100361, 2017). "Two patients with pancreatic NET were excluded from survival and progression analyses due to early death after surgical intervention; one patient had a high GLO1 copy number in primary tissue (4.13) and one had a low GLO1 copy number (0.91)." (PMID 29100361, 2017). "In the pooled GEP-NET cohort, GLO1 copy-number in healthy tissue was 2.0 in all samples but significantly increased in primary tumour tissue in 43% of patients with pancreatic NET and in 72% of patients with midgut NET, mainly driven by significantly higher GLO1 copy-number in midgut NET." (PMID 29100361, 2017). "Here, we show that in our cohort of patients with well differentiated GEP-NET, the frequency of increased GLO1 copy number was markedly higher than in other tumours investigated to date, with prevalences of 43% in pancreatic NET and 72% in midgut NET, respectively." (PMID 29100361, 2017). "GLO1 may also suppress cytotoxicity of STZ and cause MDR in chemotherapy of pancreatic NET." (PMID 29100361, 2017). "GLO1 copy-number variation was measured in 39 patients with GEP-NET (midgut NET, n = 25; pancreatic NET, n = 14) after curative or debulking surgical treatment." (PMID 29100361, 2017). "In contrast, in patients with pancreatic NET there was a very strong negative correlation of preoperative chromogranin A with GLO1 copy number in primary tumour tissue (r = - 0.94, p = 0.005)." (PMID 29100361, 2017). "In contrast, in patients with pancreatic NET, time without progression was not significantly different in patients with normal or low (< 2.4) versus increased (≥ 2.4) GLO1 copy-number repeats [log Rank (Mantel-Cox), Chi square 0.582, p = 0.46]." (PMID 29100361, 2017).
pancreatic tumor (1 paper, 2025). "IHC staining revealed that PJA1 and GLO1 were predominantly expressed in the ductal cells of the pancreatic tumor." (PMID 40908564, 2025). "Pancreatic tumors with high GLO1 expression, obtained surgically, demonstrated diminished responsiveness to IKE compared to tumors with low GLO1 expression." (PMID 40908564, 2025).